TTC23L (tetratricopeptide repeat domain 23 like)
Synonyms: FLJ25439; MC25-1
Tractability: No criterion of Open Targets' tractability assessment is met for any kind of drug.
Gene: Protein-coding gene on chromosome 5 (34,838,833 to 34,900,511, forward strand). Ensembl gene ENSG00000205838.
Subcellular location: Cytoplasm, cytoskeleton, microtubule organizing center, centrosome; Cytoplasm, cytoskeleton, spindle; Midbody
Gene Ontology:
Molecular function: protein binding
Biological process: response to endoplasmic reticulum stress
Cellular component: midbody; centrosome; spindle
Genetic constraint (gnomAD): Loss-of-function variants: 41 observed, 46.45 expected, observed/expected ratio (o/e) 0.88, 90% interval 0.69 to 1.14. The upper end of that interval is the gene's LOEUF score, 1.14, which puts it in group 5 of 6, group 1 being the genes least tolerant of losing a copy. Missense variants: 386 observed, 428.58 expected, observed/expected ratio (o/e) 0.9, 90% interval 0.83 to 0.98. Synonymous variants: 157 observed, 160.32 expected, observed/expected ratio (o/e) 0.98, 90% interval 0.86 to 1.12.
Homologues: Orthologues: chimpanzee TTC23L (98% identical), macaque TTC23L (94% identical), dog TTC23L (83% identical), rat Ttc23l (70% identical), mouse Ttc23l (68% identical), pig TTC23L (63% identical), guinea pig TTC23L (54% identical), tropical clawed frog ttc23l (41% identical). Paralogues in human: TTC23 (28% identical).
Diseases named in the same sentence as TTC23L in open-access papers:
TTC23L is named in the same sentence as 1 disease in open-access papers, as found by Europe PMC text mining. Sharing a sentence is not in itself a finding about the gene and the disease. The quoted sentences say what the papers report.
mastitis (1 paper, 2021). Inflammation of breast tissue during lactation or postpartum due to an obstructed duct or infection. "The TTC23L gene is highly expressed during lactation and is identified as a candidate gene that can affect mastitis in Holstein cows." (PMID 34394196, 2021).